RNU6-488P (RNA, U6 small nuclear 488, pseudogene)
Gene: Small nuclear RNA gene on chromosome 3 (93,843,764 to 93,843,862, forward strand). Ensembl gene ENSG00000251727.
Homologues: Orthologues: chimpanzee U6 (98% identical), macaque U6 (91% identical), guinea pig U6 (68% identical). Paralogues in human: RNU6-712P (93% identical), RNU6-16P (80% identical), RNU6-726P (80% identical), RNU6-1099P (79% identical), RNU6-1157P (79% identical), RNU6-181P (79% identical), RNU6-19P (79% identical), RNU6-1029P (78% identical), RNU6-1083P (78% identical), RNU6-1175P (78% identical), RNU6-1218P (78% identical), RNU6-12P (78% identical), and 1283 more.